TNF (tumor necrosis factor)
Diseases named in the same sentence as TNF in open-access papers (continued):
Sharing a sentence is not in itself a finding about the gene and the disease.
Obesity (continued). "Tumor necrosis factor-α (TNF-α) is one of several cytokines often elevated in rheumatologic disorders including PsA and has also been found to be elevated in patients with obesity, metabolic syndrome, diabetes, and/or atherosclerotic disease." (PMID 29721512, 2017). "and genetic and pharmacological interventions that reduce TNFα functions improved obesity and insulin resistance in vitro and vivo." (PMID 28827783, 2017). "For example, TNF-α, IL-6, PAI-1, NO, factor VII, and MCP-1 were correlated with adverse pathophysiological phenotypes associated with obesity." (PMID 29214018, 2017). "Obesity-induced pro-inflammatory cytokines and LPS polarize KC towards Mpro that in turn induce a vicious cycle of TNFα, IL-6, and IL-1β that further boosts and deteriorates liver functions." (PMID 28233125, 2017). "IL-6 and TNF-α are pro-inflammatory cytokines and were overproduced during obesity, thereby contributing to the pathogenesis of insulin resistance." (PMID 28893239, 2017). "In the murine model of obesity, the expression level of inflammatory markers including IL-1β and TNF-α as well as the macrophage marker CD68 was significantly enhanced in metabolic organs, together with CypB." (PMID 29312150, 2017). "Obesity is associated with an elevated secretion of proinflammatory cytokines, including IL-6, TNF-alpha, and C-reactive protein, and obesity is posited to be a state of chronic inflammation." (PMID 28428966, 2017). "They produce pro-inflammatory cytokines, notably tumor necrosis factor alpha (TNFα) and interferon gamma (IFNγ), and regulate macrophages to promote insulin resistance in obesity." (PMID 29163547, 2017). "There is substantive evidence supporting the notion that obesity is correlated with a chronic inflammatory response based on the identification of abnormal cytokines such as TNF-α and IL-6, along with the activation of pro-inflammatory signaling pathways." (PMID 29354072, 2017). "Among the different types of proinflammatory cytokines, TNFα is the first one identified to connect obesity, inflammation, and insulin resistance." (PMID 29230238, 2017). "Multiple pro-inflammatory cytokines including tumor necrosis factor-a (TNF-a) and IL-6 are up-regulated in cases of obesity and intensify the prevalence and the progression of CAD." (PMID 28754090, 2017). "Obesity promotes hepatic steatosis and inflammation by producing pro-inflammatory cytokines such as tumor necrosis factor (TNF)-α and interleukin (IL)-6, which are both closely related to liver carcinogenesis." (PMID 28938561, 2017). "In this study, we evaluated the role of cytokines in T2DM and obesity by measuring plasma TNF-α, IL-6, and IL-10 levels." (PMID 28225860, 2017). "To further investigate the molecular mechanism responsible for TMAO-induced cardiac fibrosis and dysfunction in WD-induced obesity, we measured the protein levels of pro-inflammatory cytokines TNF-α and IL-1β and anti-inflammatory cytokine IL-10 in the hearts." (PMID 28377725, 2017). "As obesity increased TNFα expression increased suggesting infiltration of inflammatory immune cells and exacerbation of adipose tissue inflammation." (PMID 29018280, 2017). "TNF-α is elevated in many rheumatologic disorders, including PsA, and has also been found to be elevated in patients with obesity, metabolic syndrome, diabetes, and atherosclerotic disease." (PMID 29721512, 2017). "Few studies have investigated the impact of obesity on the response to tumor necrosis factor inhibitors (TNFi) in patients with axial spondyloarthritis (axSpA)." (PMID 28724442, 2017). "The best-studied inflammatory players in obesity are TNFα and IL-6, but also include IL-17, CCL-2, and many others." (PMID 28233125, 2017). "C-reactive protein (CRP), interleukin (IL) 6, IL-8, and tumour necrosis factor alpha (TNF-α) were higher in the obesity group compared with the normal-BMI group." (PMID 28771179, 2017).
Obesity (continued). "The increase of the proinflammatory plasma cytokines TNF-α and IL-1β as well as the decrease of the anti-inflammatory plasma cytokine IL-10 displayed the low-grade inflammation status which is well known in obesity." (PMID 28357137, 2017). "As inflammation is a common feature of obesity we measured plasma levels of two cytokines associated with the progression of CVD, IL-6, and TNF-α, in our 4 groups of mice." (PMID 28184201, 2017). "In the present study, calpain inhibition reduced obesity-induced pro-inflammatory gene expression including TNFα, IL-6, and IL-1β in adipose tissue." (PMID 29089532, 2017). "We have previously reported that both IL-33 and TNF play a role in the effects of obesity on O3-induced AHR." (PMID 28704544, 2017). "At least 24 typical inflammatory mediators such as leptin, resistin, IL-6, TNF, and chemokines, among others (e.g., C-reactive protein, haptoglobin, and amyloid A) are upregulated during obesity." (PMID 28293269, 2017). "The excess accumulation of M1 macrophages within VAT is now understood to be the primary source of circulating proinflammatory cytokines IL-1β, IL-6, and TNF-α that contribute to the state of chronic, low-grade inflammation observed during obesity." (PMID 28400677, 2017). "We report that TNFα expression increased in adipose tissue dependent on the developmental stage of obesity." (PMID 29018280, 2017). "TNFα gene expression was increased in adipose tissue from epididymal depots of diet-induced obese (DIO) mice, with a progressive increase in TNFα abundance correlating with increased obesity." (PMID 29018280, 2017). "TNF-α, a proinflammatory cytokine, is increased in excessive insulin, obesity and metabolic syndrome." (PMID 29340106, 2017). "TNF-α takes part in obesity-related systemic insulin resistance by suppressing insulin receptor tyrosine kinase activity in the adipose tissue and skeletal muscle." (PMID 28626770, 2017). "Insulin resistance and obesity are characterized by a low-grade but chronic inflammatory state, with elevated circulating levels of CRP, TNF-α, IL-6 and leptin and reduced ACDC concentrations associated with increased cardiometabolic risk." (PMID 29020958, 2017). "The results demonstrated that obesity induced significantly higher expression levels of IL-6 and TNF-α in sera." (PMID 29354072, 2017). "Nonetheless, TNFR2 is suggested to cooperate with TNFR1 to regulate TNF-α signaling in chronic inflammatory conditions such as obesity, and accordingly, only TNFR2 gene expression is reported to increase in obese versus lean human adipocytes." (PMID 29186929, 2017). "To explore the potential role of Survivin in obesity-related inflammation stress, we performed RNA sequencing assays to detect the mRNA expression differences under Survivin overexpression in response TNFα challenge." (PMID 28055005, 2017). "In contrast, in conditions such as obesity, excess adipocytes directly secrete TNF-alpha, as well as produce agents that induce production of TNF-alpha such as HMGB-1." (PMID 29058588, 2017). "Leptin contributes to the inflammatory state in obesity by modulating TNF-α and activating macrophages, and butyrate reduced leptin levels in mid-adult and late-adult mice." (PMID 28686216, 2017). "Its blood levels are elevated in people with obesity, correlating with body weight and TNF-α levels." (PMID 28103807, 2017). "A decreased expression was also observed in diet-induced or genetic mouse models of obesity and this down-regulation was mimicked in vitro by TNF treatment." (PMID 29075020, 2017). "The only two overweight subjects showed a mean decrease of 34% and 23%, respectively, for CRP and TNF-α levels, while, among women with obesity (BMI > 30 kg/m2), mean increase of 39% and 5% was present, respectively." (PMID 28408969, 2017).
Obesity (continued). "TNF-α, one of the key mediators of the inflammatory response in obesity, is articulated by a number of mechanisms, namely, infiltrating macrophages, adipocytes in the hypertrophic adipose tissue, microglia and also neurons in the hypothalamus." (PMID 29176994, 2017). "As obesity is also considered an inflammatory disease, we also assessed the blood levels of pro-inflammatory cytokines IL-1β and TNFα." (PMID 28744254, 2017). "TNF-α content is increased in murine adipose tissue, and increased circulating TNF-α levels are reported in obese humans and experimental animal models of obesity." (PMID 27562094, 2016). "TNFα, a proinflammatory cytokine, has been shown to directly mediate insulin resistance in rodent models of obesity." (PMID 27583789, 2016). "Obesity is also tightly related to high levels of inflammatory mediators, including the cytokine tumor necrosis factor-alpha (TNF-α)." (PMID 27562094, 2016). "In obesity, inflammatory mediators such as IL-1β, TNF-α, and interferon gamma can elevate the CCR6 expression level." (PMID 27869712, 2016). "It is well known that obesity is a chronic inflammatory status with increased serum levels of tumor necrosis factor-α (TNF-α), interleukin-6 (IL-6), and IL-1β." (PMID 27070576, 2016). "Chronic inflammation is a characteristic of obesity that is caused because mature adipocytes inducing expression of pro-inflammatory cytokines genes including MCP-1 and TNF-α." (PMID 27792149, 2016). "Our data showing increased TNF-α, IL-18, and IL-8 expression in obesity are in agreement with studies showing induction of these proinflammatory proteins in obese humans." (PMID 27980459, 2016). "Nowadays, obesity is considered chronic, low-grade inflammation, with excess production of IL-1β, Il-6 and TNF-α." (PMID 27097934, 2016). "MCP-1 and TNF-α contribute to monocyte recruitment intro WAT and pathogenesis of obesity-linked complications in WAT, respectively." (PMID 27792149, 2016). "This skewing is thought to be due to a chronic inflammatory Th1/Th17 type milieu during obesity, with increased IL-6, TNF-α and IFN-γ." (PMID 27483441, 2016). "Obesity and T2DM are associated with a chronic inflammatory response that is characterized by increased production of TNF-α and other proinflammatory cytokines." (PMID 27746742, 2016). "Our findings highlight TNF-α and PTEN as potential targets to limit insulin resistance and vascular complications associated with obesity-related conditions." (PMID 27562094, 2016). "During obesity, pro-inflammatory macrophages accumulate in adipose tissue representing a chronic low-grade inflammation; these cells are the dominant sources of TNF promoting insulin resistance." (PMID 27148273, 2016). "In obesity a variety of cytokines such as TNFα secreted by adipose tissue can induce the Cdk5 dependent PPARγ phosphorylation." (PMID 27483259, 2016). "The obesity-induced changes in adipocyte gene expression trigger release of proinflammatory cytokines (TNF-α, MCP1) that lead to recruitment and activation of macrophages." (PMID 28004036, 2016). "IL-10 has anti-inflammatory properties and enhanced its production by adipose tissue in obesity is a defense mechanism of body to counter-regulate the pro-inflammatory actions of several inflammatory cytokines such as TNF-α, IL-6 and IL-8." (PMID 26909479, 2016). "Cells were stimulated by TNF-α or macrophage-conditioned medium to mimic an obesity-related environment where macrophage infiltration is prevalent." (PMID 27983683, 2016). "Systemic inflammation can increase during obesity, resulting in increased proinflammatory cytokines such as IL-1β and TNF-α, which induce muscle wasting." (PMID 27579157, 2016). "Factors that are elevated in obesity, such as tumor necrosis factor α (TNFα) and interleukin 6 (IL6), increase the expression and secretion of MCP-1." (PMID 28030645, 2016).
Obesity (continued). "A recent study showed that obesity mainly exerts its inhibitory effect on osteoblastogenesis by TNF-α, secreted from adipocytes." (PMID 27746742, 2016). "At 16wk of HFD-feeding, expressions of the pro-inflammatory cytokines Ccl2 and TNFα, as well as the macrophage marker F4/80 were most profoundly elevated in gWAT, suggesting that clock gene damping within this tissue may be linked to the development of obesity-related inflammation." (PMID 27439882, 2016). "Taken together, our study suggests that in obesity, TNF-α induces vascular insulin resistance by increasing PTEN activity that negatively modulates Akt/eNOS/NO signaling and insulin vasodilation." (PMID 27562094, 2016). "Subclinical inflammation plays a critical role in the pathogenesis of Type 2 diabetes and insulin resistance syndrome, whereby pro-inflammatory cytokines such as TNF-α levels are increased in obesity and Type 2 diabetes." (PMID 27532642, 2016). "Hotamisligil and colleagues first demonstrated that within obesity, TNF-α was a key player in insulin resistance." (PMID 27128935, 2016). "In obesity, macrophages infiltrate adipose tissue and begin to induce proinflammatory cytokines, such as IL-1β, TNFα, and IL-6, which contribute to insulin resistance." (PMID 27066503, 2016). "As obesity is a low-grade inflammation, and EA has shown to have an anti-obesity effect, we measured important inflammatory markers such as TNF-α, IL-6 and CRP, in our patients, during EA treatment." (PMID 27136447, 2016). "It was reported that adipose-derived TNF-α levels in mice were increased during the advancement of obesity, but when TNF-α was neutralised, insulin sensitivity was improved." (PMID 26770659, 2016). "In conclusion, significant biomarkers of inflammation (TNFα, IL-6, hsCRP, and haptoglobin) and endothelial dysfunction (sICAM-1 and sVCAM-1) are present in young patients with diabetes, obesity, and dyslipidemia." (PMID 27459718, 2016). "The overexpression of crucial pro-inflammatory cytokines, e.g., TNFα, IL-6 and MCP-1, which is associated with the state of obesity, is closely connected to insulin resistance as well as diabetes mellitus 2 or cardiovascular syndrome development." (PMID 27983705, 2016). "In genetic mouse models of obesity, macrophage pAMPK expression was 33% lower than lean controls, with markedly increased TNF-α secretion." (PMID 27128935, 2016). "TNF-α is one of the primary mediator of the inflammatory response in obesity and insulin resistance." (PMID 27246393, 2016). "It is well accepted that obesity has an inflammatory status, including an elevation of the proinflammatory cytokines, TNF-α, IL-1β, and IL-6 in adipose tissues and sera." (PMID 27095436, 2016). "Both TNF and IL-6 are correlated with the body mass index (BMI), and TNF is known to play a role in obesity and in particular in the insulin resistance and diabetes that often accompany obesity." (PMID 27148273, 2016). "IL-17A can induce expression of TNF-α, IL-6, and IL-1β cytokines, which are found with increased levels in obesity." (PMID 27070576, 2016). "In these cases, the antioxidant action of GTCs is likely involved in their anti-obesity mechanism owing to the fact that ROS stimulate nuclear factor-κB, which in turn promotes the expression of proinflammatory cytokines, such as TNF-α and IL-1β." (PMID 27689985, 2016). "The cellular level of DsbA-L is negatively correlated with obesity in mice and human, and its expression is stimulated by insulin sensitizer rosiglitazone but inhibited by the inflammatory cytokine TNF-α." (PMID 27795806, 2016). "NAFLD pathophysiologic processes linking obesity enhanced circulating concentrations of pro-inflammatory cytokines and factors (e.g., TNF-α, IL-6 and IL-1β)." (PMID 27483220, 2016). "The pro-inflammatory cytokines TNFα, IL-1β, and IL-6, considered as highly involved in obesity-related IR and the anti-inflammatory cytokines IL-4 and IL-10 displayed similar levels in CT, OIS, and OIR subjects." (PMID 27111539, 2016).
Obesity (continued). "Obesity and nutrient overload can trigger proinflammatory cytokines, such as tumor necrosis factor-alpha (TNF-α) and interleukin (IL)-1β, to build up in a number of affected tissues." (PMID 26869995, 2016). "For example, TNF-α is an important mediator of insulin resistance in obesity owing to its inhibitory effects on insulin receptor signaling." (PMID 27213439, 2016). "Some studies have reported that TNF-α is related to the stimulation of adipose lipolysis in obesity." (PMID 26912161, 2016). "Obesity is considered a chronic low-grade inflammation state with increased pro-inflammatory cytokine, e.g., TNFα." (PMID 27656148, 2016). "Low-grade lingering inflammation (e.g., increased levels of TNF-α and IL-6) and protein and lipid oxidation are commonly reported in individuals who have obesity." (PMID 27440160, 2016). "Other studies have shown that inflammatory cytokines known to be elevated in obesity (e.g. IL1β, TNF-α, and IL6) impair lymphatic collecting vessel contraction capacity, and, in the case of IL1β, do so by induction of iNOS expression." (PMID 26796537, 2016). "Another proinflammatory cytokine secreted by epicardial fat, which is also elevated in obesity and actually worsens insulin resistance, is TNF-α (OMIM 191160)." (PMID 27213076, 2016). "Since vascular insulin resistance represents a primary defect in vascular dysfunction, TNF-α and PTEN are potential therapeutic targets for obesity-associated cardiovascular and metabolic dysfunction." (PMID 27562094, 2016). "In fact, increased circulating levels of pro-inflammatory mediators such as C-reactive protein (CRP), tumor necrosis factor α (TNFα), monocyte chemoattractant protein-1 (MCP-1) and interleukin-6 (IL-6) have been observed in obesity-associated IR." (PMID 27111539, 2016). "The link between obesity and inflammation has been derived from the finding that proinflammatory cytokines tumor necrosis factor alpha (TNF-α) and interleukin 6 (IL-6) are overexpressed in obesity." (PMID 26829184, 2016). "TNF-α produced by obesity-induced inflammation stimulates IKK41, JNK42, and mTOR/S6K43, 44, which enhance serine phosphorylation of insulin receptor substrate-1 (IRS-1)." (PMID 26316333, 2015). "It was separately reported by two different studies that plasma and adipose tissue levels of IL-6 correlated better than TNF-α with obesity and insulin resistance." (PMID 26200663, 2015). "In support of this, ZIP14 down-regulation was correlated with the expression of several cytokines produced in unhealthy adipose tissue as part of the inflammatory response in obesity, i.e., TNF-α and IL-10." (PMID 26623077, 2015). "The pathogenesis of obesity-related atherosclerosis, which is marked by hypoadiponectinemia and high serum levels of leptin and TNF-α in overweight and obese individuals, serves an important function in the initiation of inflammation." (PMID 26011530, 2015). "One study showed that BMI was the only predictor of hs-CRP levels and TNF-α levels (all P<0.001), considering that obesity induced an increase in certain inflammatory markers in the serum." (PMID 26087062, 2015). "On the other hand, adiponectin is inversely correlated with obesity and has a protective effect against insulin resistance as it exhibits anti-inflammatory properties by reducing TNF-α and IL-6 secretion from macrophages." (PMID 26003803, 2015). "HFD induced obesity and inflammation (TNF-α) resulting in fibrosis and decreased percentage ejection fraction." (PMID 25954207, 2015). "As observed in mice models of diet-induced obesity, TLR4 deficiency prevented the enhanced release of TNF-α and IL6 in our hypoxic mice." (PMID 25873766, 2015). "Subsequent animal studies with KO have included a wide range of models such as ulcerative colitis, depression, obesity, and myocardial infarction in rats, or tumor necrosis factor-alpha (TNFα)-overexpression, rheumatoid arthritis, and dietary obesity in mice." (PMID 25961320, 2015).